ANGPTL8 (angiopoietin like 8)
Diseases named in the same sentence as ANGPTL8 in open-access papers (continued):
Sharing a sentence is not in itself a finding about the gene and the disease.
diabetes (continued). "Besides, the findings obtained that correlate ANGPTL8 plasma levels and diabetes control are also discrepant." (PMID 32069954, 2020). "Regardless, this study is the first report showing that ANGPTL8 could be a potential biomarker for death prediction in patients with diabetes." (PMID 32746907, 2020). "Furthermore, the inclusion of ANGPTL8 in QFrailty score significantly improved its predictive performance for mortality in patients with diabetes." (PMID 32746907, 2020). "The linear relationship of ANGPTL8 with mortality was only observed in the patients with diabetes." (PMID 32746907, 2020). "However, ANGPTL8 better predicts the risk for all-cause mortality, CVD-related mortality and CVD events compared with several traditional risk factors for CVD in diabetes, such as BMI, HbA1c, HOMA-IR, TG and total cholesterol." (PMID 32732946, 2020). "Further investigation is required to assess whether circulating ANGPTL8 levels reflect pathology of diabetes." (PMID 29538435, 2018). "ANGPTL8 expression pattern in some pathological conditions such as obesity, diabetes, and MS remains unclear." (PMID 29719529, 2018). "Studies have reported that ANGPTL8 concentrations are significantly and positively associated with triglycerides (TG) and LDL-C levels but inversely associated with HDL-C levels in patients with diabetes." (PMID 30021605, 2018). "We demonstrated a significantly elevated serum ANGPTL8 level in IGR subjects, suggesting that ANGPTL8 might play a role before developing into diabetes mellitus." (PMID 29082263, 2017). "ANGPTL3 was associated with ANGPTL8 in the non-diabetic subjects, whereas, ANGPTL4 was associated with ANGPTL8 in the obese subjects regardless of their diabetes status." (PMID 27733177, 2016). "Accumulating evidence suggests that circulating ANGPTL8 is elevated in diabetes." (PMID 27053679, 2016). "ANGPTL8 has been suggested as a potential target for β-cell regenerative therapy in diabetes." (PMID 26739706, 2016). "However, considering the fact that there are multiple inquiries that need to be addressed: Is the elevated level of ANGPTL8 and the reduced level of ADPQ in association with MetS considered a causal factor or an effect of MetS and its associated complications, such as diabetes and CVD?" (PMID 37767256, 2023). "Therefore, the relatively low level of ANGPTL8 in the MOD cluster might be due to the low age at diabetes onset." (PMID 32732946, 2020). "Furthermore, a linear relationship between ANGPTL8 levels and risk for all-cause mortality in diabetic patients, but not in control subjects, clearly indicated that ANGPTL8 was a strong predictor of all-cause mortality in patients with diabetes." (PMID 32746907, 2020). "ANGPTL8, which is a novel protein that has been proposed to serve as an important regulator of glucose and lipid metabolism, might play an important role in the progression of diabetes." (PMID 32732946, 2020). "We aimed to investigate the associations between ANGPTL8 and lipids in people without diabetes." (PMID 30021605, 2018). "This suggested that ANGPTL8 might act as a predictive marker in prediabetes and diabetes mellitus." (PMID 29082263, 2017). "Future studies are needed to elucidate the link between ANGPTL8 and IGFBP4 and the mechanism of action through which they contribute to diabetes and its complications." (PMID 37762544, 2023). "Therefore, the difference in the ANGPTL8 levels among the novel diabetes groups might be due to their correlation with the metabolic characteristics in each cluster, such as higher FPG in SIDD, higher TG in SIRD, and old age in MARD, and could further lead to a detrimental outcome." (PMID 32732946, 2020). "Previous studies have also demonstrated that ANGPTL8 is closely related to inflammation, which is increasingly considered a pathologic mediator of CVD, diabetes and its complications." (PMID 32732946, 2020).
diabetes (continued). "Patients with diabetes and coronary artery disease (CAD) have remarkably higher levels of ANGPTL8 than those with only diabetes." (PMID 29940978, 2018). "Long-term controversy regarding the role of angiopoietin-like protein 8 (ANGPTL8) in beta-cell proliferation and diabetes progression made it a research spotlight." (PMID 29719529, 2018). "ANGPTL8 levels are significantly and positively related to TG and LDL-C levels, but inversely related to HDL-C levels in children and patients with diabetes." (PMID 29940978, 2018). "Circulating ANGPTL8 levels are significantly increased in patients with nonalcoholic fatty liver disease and type 2 diabetes mellitus." (PMID 39019343, 2024). "The results highlight that an elevated level of ANGPTL8 in diabetes led to neither elevation in insulin production nor an alteration in glucose levels." (PMID 37755252, 2023). "Based on meta-analyses of a non-obese population, circulating ANGPTL8 concentrations in patients with type 2 diabetes mellitus are elevated compared with non-diabetic adults." (PMID 30021605, 2018). "Multivariate linear regression analysis controlling for age, sex and BMI further revealed that duration of diabetes, TG, eGFR and ACR were independently related to serum levels of ANGPTL8 in the subgroups of type 2 diabetic patients with A2 and A3 (all P < 0.05)." (PMID 30072957, 2018). "Serum ANGPTL8 levels were determined using ELISA in 22 subjects with NGT (normal glucose tolerance), 74 subjects with IGR (impaired glucose regulation), and 33 subjects with T2DM (type 2 diabetes mellitus)." (PMID 29082263, 2017). "We expressed mouse ANGPTL8 using adenovirus in 2 mouse models of diabetes (streptozotocin and Non-Obese Diabetic (NOD) mice) over 2 weeks." (PMID 31741751, 2016). "ANGPTL8 is related to HDL-C dysfunction and is involved in the association between dyslipidaemia and arteriosclerosis, regardless of glucose intolerance or diabetes mellitus." (PMID 32746907, 2020). "As shown by partial correlation analysis, serum levels of ANGPTL8 were positively and significantly correlated with TG, duration of diabetes and c-IMT in type 2 diabetic patients with and without subclinical atherosclerosis groups (all P < 0.05) after adjustment for age, sex and BMI." (PMID 30007407, 2018). "Therefore, we investigated full-length circulating ANGPTL8 levels in patients with CAD and the association between ANGPT8 levels and severity of CAD in Chinese individuals without diabetes." (PMID 29940978, 2018). "Therefore, in this study, we investigated circulating full-length ANGPTL8 levels in patients with CAD and the association between ANGPT8 levels and the severity of CAD in Chinese individuals without diabetes." (PMID 29940978, 2018). "No convincing evidence could be found to support the direct effects of ANGPTL8 on beta-cell replication, and thus ANGPTL8 is not regarded as a possible target for diabetes intervention." (PMID 29719529, 2018). "Multivariate regression analysis showed that TG, duration of diabetes and c-IMT were independently related factors influencing serum levels of ANGPTL8 in both type 2 diabetic patients with and without subclinical atherosclerosis groups." (PMID 30007407, 2018). "We have confirmed the pancreatic beta cell proliferation induced by ANGPTL8, but it was not able to reverse diabetes in rats with STZ- induced diabetes or obese rhesus monkey with naturally occurring diabetes [data not shown]." (PMID 27823982, 2016).
Obesity (48 papers, 2016 to 2025). Accumulation of substantial excess body fat. "ANGPTL8 levels are closely related to obesity-associated cardiometabolic risk factors, emerging as a potential biomarker of IR and T2DM." (PMID 40282999, 2025). "Further studies on multiple populations are needed to confirm the role of ethnicity in the association between ANGPTL8 and obesity." (PMID 38189043, 2023). "ANGPTL8 plays an important role in lipid and glucose metabolism and is widely associated with various metabolic disorders, such as obesity and T2D, with more recent studies highlighting its role in inflammation." (PMID 37947641, 2023). "There are reports in the literature about the role of ANGPTL8 in the development of obesity, which is the main cause of the development of insulin resistance, and thus type 2 DM." (PMID 36983346, 2023). "ANGPTL8 is a potential early marker for adolescent obesity and is associated with well-known obesity and inflammatory markers." (PMID 38189043, 2023). "Plasma ANGPTL8 concentrations are associated with obesity, type 2 diabetes, and nonalcoholic fatty liver." (PMID 36034432, 2022). "All results indicate that upregulation of ANGPTL8 expression is associated with the incidence of obesity." (PMID 36034432, 2022). "Obesity was associated with low plasma ANGPTL8 concentrations (normal weight 32.45 ± 5.57 vs. obesity 19.69 ± 1.49 ng/mL, p = 0.004), regardless of the degree of insulin resistance." (PMID 34884755, 2021). "Plasma concentrations and hepatic expression of ANGPTL8 were increased in patients with obesity-associated NAFLD in relation to the degree of hepatic steatosis." (PMID 34884755, 2021). "In this study, we have shown for the first time that IT causes an increase in the ANGPTL8 plasma level in rats with diet-induced obesity." (PMID 34035808, 2021). "In the clinical view of Angptl8 regulation, elevation of circulating Angptl8 was associated with polycystic ovary syndrome, hypertension, obesity, and type 2 diabetes." (PMID 31470507, 2019). "Our and other research groups have recently shown that ANGPTL8 levels is increased in T2D as well as in obesity, which suggests the pathogenic role of this protein in these diseases." (PMID 30524367, 2018). "Both our and other research groups have shown that ANGPTL8 is associated with insulin resistance and that its levels are increased in obesity, metabolic disease, and T2D." (PMID 30524367, 2018). "Our group and others recently demonstrated that ANGPTL8 levels were increased in T2D as well as obesity, suggesting a pathogenic role for this protein in these diseases." (PMID 29490644, 2018). "As such, this study was designed to investigate the relationship between ANGPTL8 levels and adiposity, metabolic homeostasis and liver steatosis in association with obesity and the PWS condition." (PMID 28600576, 2017). "We have recently showed that both forms show a similar trend in obesity and their level was reduced after exercise, however, only full length ANGPTL8 showed association with FBG." (PMID 26850725, 2016). "In order to understand the effect of obesity on the association between the ANGPTL8 and HsCRP, the population was divided according to BMI into non-obese and obese subjects." (PMID 26850725, 2016). "Obesity and serum TG levels are decreased in mice with ANGPTL8 deficiency." (PMID 39274442, 2024). "TSH variations due to increasing leptin, ANGPTL8, and TyG index may enhance the risk of insulin resistance diseases, such as obesity and CVD, in Saudi females with T2DM." (PMID 39252284, 2024). "In this study, we aimed to assess the circulating levels of ANGPTL8 in adolescents with overweight or obesity in comparison to its levels in normal-weight adolescents; and to investigate its associations with the levels of some established obesity markers." (PMID 38189043, 2023).
Obesity (continued). "Therefore, further investigations are needed to establish the role of ANGPTL8 in the development of childhood obesity and the nature of its association with inflammatory and obesity markers." (PMID 38189043, 2023). "In fact, ANGPTL8 deficiency in mice reduces serum TG levels and obesity." (PMID 38303975, 2023). "We hypothesize that, like our earlier observations in adults, plasma ANGPTL8 levels are positively associated with obesity and hsCRP in adolescents." (PMID 38189043, 2023). "To evaluate whether ANGPTL8 expression is associated with obesity, we first analyzed publicly available transcriptomic data of subcutaneous adipose tissue from a cohort of obese individuals extracted from the GEO database." (PMID 36034432, 2022). "Both SG and RYGB induce the downregulation of angiopoietin-like 8 (ANGPTL8), which inhibits lipogenesis in human hepatocytes when exposed to lipotoxic conditions and is associated with the degree of steatosis in the livers of rats with diet-induced obesity." (PMID 36204626, 2022). "Elevated ANGPTL4 and ANGPTL8 levels are also associated with obesity." (PMID 34293055, 2021). "Furthermore, hepatic mRNA and protein expression of ANGPTL8 was upregulated in patients and rat models with obesity-associated NAFLD in relation to the degree of hepatic steatosis." (PMID 34884755, 2021). "Taken together with these findings, ANGPTL8 secreted from adipocytes may underlie increases in circulating ANGPTL8 levels seen in obesity." (PMID 29538435, 2018). "Our findings ultimately support a model in which ANGPTL8 upregulated the expression of PPARγ and c/EBPα by inhibiting the Wnt/β-catenin signaling pathway and promoting the adipogenic differentiation of MSCs, resulting in lipid deposition in multiple organs and causing obesity in male mice." (PMID 36034432, 2022). "Estrogen can significantly inhibit the expression of ANGPTL8 in the liver, which explains why men are more prone to obesity than women and suggests that some diseases in men caused by abnormal fat metabolism may be prevented by blocking the expression of ANGPTL8." (PMID 36034432, 2022). "Constant feeding increases circulating ANGPTL8 levels, which leads to increased adipose storage (obesity) and hypertriglyceridemia." (PMID 39274442, 2024). "The study will also assess thyroid hormones and leptin, angiopoietin like 8 (ANGPTL8), obesity, and cardiovascular diseases (CVD) in T2D patients." (PMID 39252284, 2024). "Similar to the observed increase in plasma levels of ANGPTL8 in individuals with obesity from our study cohort, plasma levels of hsCRP were also observed to be significantly higher in participants with obesity compared to those of normal-weight and overweight." (PMID 38189043, 2023). "Even when the analysis was stratified by sex, statistically significant elevated levels of ANGPTL8 were observed in female and male individuals with obesity compared to normal-weight individuals." (PMID 38189043, 2023). "A prospective cohort study assessed the serum levels of both ANGPTL3 and ANGPTL8 in Korean children in the context of obesity and lipid profiles." (PMID 38189043, 2023). "ANGPTL8 level had a reasonable prognostic power for obesity with an AUC of 0.703 (95%-CI=0.648-0.759)." (PMID 38189043, 2023). "Numerous studies have shown that the concentration of ANGPTL8 is increased in persons with obesity, MS and DM." (PMID 36983346, 2023). "ELISA and bead-based multiplexing assays were used to measure plasma levels of ANGPTL8 and other inflammation and obesity-related biomarkers." (PMID 38189043, 2023). "Having seen a positive correlation between ANGPTL8 levels and adult obesity, and positive correlations between ANGPTL5 and obesity levels in Arab children, we were motivated to examine the ANGPTL8 levels in the context of adolescent obesity." (PMID 38189043, 2023). "Studies have revealed that liver- and adipose-derived ANGPTL8 play distinct roles in regulating lipid metabolism and obesity." (PMID 37188659, 2023).
Obesity (continued). "The odds ratio [OR (95% CI)] for individuals characterized with upper tertile of ANGPTL8 level was 1.95 (1.04-3.66) for being in the overweight group and 7.08 (3.81-13.1) for being in the obesity group." (PMID 38189043, 2023). "In man circulating ANGPTL8 levels correlate with obesity and interestingly also with the human GCKR rs1260326 variant." (PMID 37031802, 2023). "In the previous study from our group, we noticed significantly higher levels of ANGPTL8 in apparently healthy women with obesity whereas ANGPTL3 levels were comparable." (PMID 35736472, 2022). "Their results suggest that hepatic secretion of ANGPTL8 is the main source of its role in regulating lipid metabolism and obesity." (PMID 36034432, 2022). "Estrogen can inhibit the expression of ANGPTL8 to counteract the effect of ANPTL8 KO on obesity in female mice." (PMID 36034432, 2022). "Old BAT showed decreased gene expression related to the lipid metabolism, such as stearoyl-CoA desaturase 2 (Scd2) and angiopoietin-like 8 (Angptl8), and increased gene expression related to obesity in WAT, such as Peg3." (PMID 34884947, 2021). "Based on the available literature data regarding the concentration of circulating ANGPTL8 in obesity and T2DM, such results suggest that this protein is associated with intrinsic energy intake and expenditure." (PMID 34035808, 2021). "Transcript levels of rat ANGPTL8 were significantly increased (p < 0.05) in the liver of rats with diet-induced obesity compared to lean control rats." (PMID 34884755, 2021). "These prior reports prompted us to study the plasma level of native ANGPTL8 as an indicator of metabolic changes after IT surgery in diet-induced obesity." (PMID 34035808, 2021). "In our hands, plasma ANGPTL8 concentrations were elevated in obesity-associated NAFLD and negatively correlated with HDL cholesterol, confirming the inseparable association between ANGPTL8 and lipid disorders." (PMID 34884755, 2021). "In this study, obesity significantly increased ANGPTL8 concentrations only in females, and a positive correlation between ANGPTL8 and BMI in this group was observed." (PMID 34959891, 2021). "Our study also reveals a positive correlation of circulating human ANGPTL8 levels with obesity, consistent with a previous study of human subjects." (PMID 29538435, 2018). "Alterations in ANGPTL8 level were found in subjects with obesity, but the pattern of alteration was controversial." (PMID 29719529, 2018). "In the current study, we observed lower circulating levels and less interindividual variability of ANGPTL8 in PWS when compared to subjects with common obesity." (PMID 28600576, 2017). "The present study analysed the association between ANGPTL8 levels and adiposity, metabolic profile and liver steatosis in relation to the adult PWS condition and obesity." (PMID 28600576, 2017). "The present study investigated circulating ANGPTL8 in PWS and controls with common obesity, assessing its association to liver steatosis." (PMID 28600576, 2017). "We have recently showed that ANGPTL8 was increased in obesity and T2D and correlated with TG level in humans." (PMID 28264047, 2017). "Obesity has also been shown to increase the level of ANGPTL8 by some studies while others showed a decrease." (PMID 26784326, 2016). "In conclusion, our data demonstrate that ANGPTL8 was increased in obesity and reduced after exercise training supporting the potential therapeutic benefit of reducing ANGPTL8." (PMID 26784326, 2016). "Our current data is in line with what has been reported about the increased ANGPTL8 level in obesity and T2D." (PMID 26850725, 2016). "Initial studies suggested that ANGPTL8 was increased in obesity and knockdown of ANGPTL8 resulted in weight reduction in addition to reduction in TG level." (PMID 26784326, 2016).